CHEK2 (checkpoint kinase 2)
Diseases named in the same sentence as CHEK2 in open-access papers (continued):
Sharing a sentence is not in itself a finding about the gene and the disease.
melanoma (45 papers, 2006 to 2025). A malignant, usually aggressive tumor composed of atypical, neoplastic melanocytes. "While there is no strong evidence that CHEK2 mutations increase the risk of melanoma, two cases of germline CHEK2 mutations in UM patients have been reported." (PMID 40283643, 2025). "PTVs in CHEK2 were associated with three cancers at p<0.001 (breast, prostate, HD) and six at p<0.05 (oesophagus, melanoma, ovary, kidney, DNHL, myeloid leukaemia)." (PMID 39209703, 2024). "Several studies have also identified an association between CHEK2 variant p.(Thr367MetfsTer15) and increased melanoma risk." (PMID 39669616, 2024). "Numerous other associations have been observed for specific cancers for CHEK2 heterozygotes including sarcoma, stomach, male breast, melanoma, endometrial and testicular cancer." (PMID 39371170, 2024). "Altogether, 7/11 double mutation carriers (excluded from the analysis of clinicopathological data) carried at least one mutation in high-risk melanoma (POT1/CHEK2) or syndromic (ATM/WRN, BRCA1, BRCA2 (2x), CHEK2/RAD51D, NBN) genes." (PMID 33050356, 2020). "Transcripts associated with BRCA1, BRCA2, ATM and CHEK2 showed altered expression in melanoma cell lines after cisplatin treatment." (PMID 23940574, 2013). "The same could be said of CHEK2 as documented in a recent meta-analysis evaluating the association of germline CHEK2 mutations with melanoma." (PMID 33050356, 2020). "A total of 9 patients (3.4%) carried mutations in high-to-moderate melanoma risk genes (CDKN2A, POT1, ACD) and 22 (8.3%) patients in other cancer syndrome genes (NBN, BRCA1/2, CHEK2, ATM, WRN, RB1)." (PMID 33050356, 2020). "The final 83 pathogenic/likely pathogenic (P/LP) germline variants (66 unique) in 71/264 (26.8%) melanoma patients were detected in 42/217 targeted genes and included five copy number variants (CNV; two in CHEK2 and SLC45A2, respectively, and one in TRPM1)." (PMID 33050356, 2020). "The two cases with VUS in CHEK2 had premenopausal familial BC and early-onset BC (38 years), melanoma, and positive family history for OC and uterine cancer, respectively." (PMID 32957588, 2020). "Although RAD54B, BLM and CHEK2 genes are mutated in CRC, they are also mutated in numerous additional cancers including pancreatic (~16.5% collectively), prostate (~16.7%), melanoma (~15.1%) and endometrial (~8.8%)." (PMID 26318585, 2015). "The authors concluded that individuals with CHEK2*1100delC heterozygosity have a twofold risk of melanoma compared with non-carriers (OR 2.01 (1.03–3.91) in the Danish, 1.42 (0.46–4.31) in Germans, and 1.79 (1.02–3.17) in the Danish and Germans combined)." (PMID 40283643, 2025). "To date, the association between CHEK2 alteration and skin cancer (both melanoma and nonmelanoma) is still unclear." (PMID 37628581, 2023). "Furthermore, a member of the Fanconi anemia pathway, CHEK2, was enriched for deletions in mucosal melanoma." (PMID 32825510, 2020). "Previous studies have demonstrated that CHEK2 c.1100del heterozygotes have a two-fold risk of malignant melanoma compared to non-carriers, while no clear associations have emerged between Mullerian sarcomas or, more generally, isolated uterine tumors and CHEK2." (PMID 32957588, 2020).
melanoma (continued). "A highly significant overlap of transcript expression in melanoma cell lines after cisplatin treatment with transcripts involved in DNA repair and DNA damage response genes BRCA1, BRCA2, ATM and CHEK2 was observed, which may be compensating for diminished NER capacity." (PMID 23940574, 2013).
glioma (43 papers, 2011 to 2026). A benign or malignant brain and spinal cord tumor that arises from glial cells (astrocytes, oligodendrocytes, ependymal cells). "Next, we investigated the mechanism/s underlying the enhanced gene expression of antigen presentation and type 1 interferon (IFN1) in glioma cells associated with Chek2 loss." (PMID 36949040, 2023). "CHEK2 deficiency in gliomas points to this possible alternative pathway." (PMID 40492861, 2025). "To investigate whether correlations seen in human GBM patients have a causal relationship, we generated a Chek2 KO clone in the GL261 mouse glioma cell line using the CRISPR cas9 system." (PMID 36949040, 2023). "CHEK2 mutations have also been found in some brain tumors, such as meningioma or glioma." (PMID 32570972, 2020). "Mutations in the CHEK2 gene may be a risk factor for gliomas, but this link requires further study." (PMID 40867242, 2025). "Consistent with this, our findings showed that low CHEK2 expression in glioma tumor cells was correlated with higher T-cell infiltration and upregulation of the antigen presentation pathway." (PMID 40492861, 2025). "We found the enhanced presentation of MHCI-bound SIINFEKL peptide on the surface of IFN-γ treated Chek2 KO glioma cells as compared to NTC cells." (PMID 36949040, 2023). "Mechanistically, loss of Chek2 enhances antigen presentation, STING pathway activation and PD-L1 expression in mouse gliomas." (PMID 36949040, 2023). "To further validate our initial CRISPR screen, we performed a second, independent CRISPR screen using GL261 glioma model where we quantified the Chek2 KO clones in intracranial gliomas in WT and CD8 KO mice hosts over time." (PMID 36949040, 2023). "IFN-γ treated Chek2 KO glioma cells induced enhanced proliferation of OT-I CD8+ T cells while it failed to activate CD8+ T cells from WT C57BL/6 mice." (PMID 36949040, 2023). "In other words, out of all the kinases, knockout of Chek2 in glioma tumor cells sensitizes them to CD8 T-cell-mediated killing." (PMID 36949040, 2023). "Overall, genetic depletion of Chek2 in tumor cells showed a modest improvement in response to PD-1 blockade in mouse GL261 glioma model." (PMID 36949040, 2023). "Significant improvement in survival was seen in mice injected with GL261 Chek2 KO gliomas treated with anti-PD-1 as compared to IgG treated animals with 30% long-term survivors (LTS) (p < 0.05)." (PMID 36949040, 2023). "Concomitantly, IFN-γ treated Chek2 KO glioma cells induced enhanced proliferation of OT-I CD8+ T cells as compared to the NTC cells (“OT-I CD8 T” panel)." (PMID 36949040, 2023). "Glioma clones with Chek2 KO were the most depleted sgRNAs in mice with intact immunity as compared to the CD8 KO mice (p < 0.0001)." (PMID 36949040, 2023). "In this study, we characterize the effect of Chek2 inhibition/depletion on the response to PD-1 or PD-L1 blockade in the murine glioma models." (PMID 36949040, 2023). "We evaluated the ability of Chek2 depleted glioma cells to present MHCI restricted OVA peptide-SIINFEKL and activate SIINFEKL-specific OT-I CD8+ T cells." (PMID 36949040, 2023). "Mechanistically, loss of Chek2 enhances antigen presentation, STING pathway activation, and PD-L1 expression in mouse gliomas, supporting Chek2 as a promising target for enhancement of response to immune checkpoint blockade therapy in glioblastoma (GBM)." (PMID 38162677, 2023). "Checkpoint kinase 2 (Chek2) mediates therapeutic resistance to CD8+ T cell recognition, and both genetic depletion or pharmacologic inhibition of Chek2 increase survival in combination with immune checkpoint blockade through STING activation in preclinical glioma models." (PMID 39295301, 2024). "Further, to investigate whether these correlations seen in human GBM patients have a causal relationship, we transfected the antigen reporter ovalbumin into both NTC and Chek2 KO cells in mouse glioma cell line GL261." (PMID 36949040, 2023).
glioma (continued). "Next, we performed a similar survival study with GL261 NTC and Chek2 KO glioma cells." (PMID 36949040, 2023). "Genetic depletion or pharmacological inhibition of Chek2 with blood-brain-barrier permeable drugs that are currently being evaluated in clinical trials, in combination with PD-1 or PD-L1 blockade, lead to survival benefit in multiple preclinical glioma models." (PMID 36949040, 2023). "Given the immune evasive function of Chek2 in glioma cells, we investigated whether Chek2 expression could influence glioma response to PD-1 blockade." (PMID 36949040, 2023). "Single-gene knock-out and overexpression studies of CHEK2, YBX1, and YBX3 in multiple glioma cell lines revealed that these proteins positively regulate each other’s expression." (PMID 40161682, 2025). "Here, based on an in vivo kinome knockout CRISPR screen, the authors show that checkpoint kinase 2 promotes CD8 T cell immune evasion and that its depletion or inhibition improve survival and response to PD1/PDL1 blockade in preclinical glioma models." (PMID 36949040, 2023). "As in the case of CHEK2, glioma cell expression of ATM, the upstream activator of CHEK2, also exhibited a T-cell phenotype similar to CHEK2 expression." (PMID 36949040, 2023). "We found that Chek2 inhibition/depletion resulted in activation of the STING pathway, as marked by the phosphorylation of TBK1 and upregulation of PD-L1 surface levels in GL261 and NPA glioma cell lines." (PMID 36949040, 2023). "Both Chek2 KO and inhibition of Chek2 kinase activity (with pharmacological inhibitors) demonstrated the same effect on STING pathway activation and expression of PD-L1 in two different glioma cell lines." (PMID 36949040, 2023). "Similar to the first CRISPR screen, the second CRISR screen demonstrated that the selection of Chek2 KO glioma cells over time is specific to WT mice and is absent in CD8 KO mice." (PMID 36949040, 2023). "This phenomenon was predominantly dependent on antigen presentation, as IFN-γ treated Chek2 KO glioma cells failed to activate CD8+ T cells from WT C57BL/6 mice (“WT CD8 T” panel)." (PMID 36949040, 2023).
breast tumors (37 papers, 2005 to 2025). "Τhe majority of CHEK2-associated breast tumors are hormone receptor positive; however, relevant clinical outcomes are not well defined." (PMID 33925588, 2021). "Overall, our study identified 19 ATM mutation carriers with 24 breast tumors and 17 CHEK2 mutation carriers with 22 breast tumors." (PMID 33919281, 2021). "Among carriers of CHEK2 truncating variants, 50% (12/24) and 46% (11/24) of primary breast tumors were grade III and II, respectively." (PMID 33925588, 2021). "The vast majority of CHEK2-associated breast tumors were hormone receptor positive, underlying a possible benefit from chemoprophylaxis with tamoxifen." (PMID 33925588, 2021). "On the other hand, among carriers of CHEK2 missense variants, 45% (5/11) and 36% (4/11) of primary breast tumors were grade III and II, respectively." (PMID 33925588, 2021). "In 2011, Taru A. Muranen reported that 34 OR genes were overexpressed in breast tumors with the CHEK2 1100delC mutation." (PMID 31781505, 2019). "Here, we report a study investigating thoroughly the prognostic associations of CHEK2:p.I157T as well as pathologic characteristics and genomic gene expression profiles of breast tumors from carriers of germ line p.I157T." (PMID 27716369, 2016). "Very few breast tumors from 1100delC carriers show CHEK2 protein expression although LOH of the wild-type allele is infrequently found." (PMID 26553136, 2015). "Here we report the first study investigating CHEK2 1100delC-related tumorigenesis by comparing gene-expression profiles and genomic changes in breast tumors of CHEK2 1100delC-mutation carriers to those of patients negative for any known germline mutations." (PMID 21542898, 2011). "Differences in the expression of the 188 CHEK2 1100delC-associated genes divided breast tumor samples from three independent datasets into two groups that differed in their relapse-free survival time." (PMID 21542898, 2011). "This study concentrated on genomic-level changes that were associated with the 1100delC germline mutation, whereas previous studies have shed light on the CHEK2 protein expression in breast tumors." (PMID 21542898, 2011). "We investigated gene copy-number aberrations and gene-expression profiles that are typical for breast tumors of CHEK2 1100delC-mutation carriers." (PMID 21542898, 2011). "We investigated the genomic copy number and gene-expression profiles of breast tumors of CHEK2 1100delC-mutation carriers." (PMID 21542898, 2011). "Our results suggest the WNT pathway as a driver of tumorigenesis in breast tumors of CHEK2 1100delC-mutation carriers and a role for the olfactory receptor protein family in cancer progression." (PMID 21542898, 2011). "Among the 75 patients with metachronous tumors of the breast and the colorectum successfully studied, 2 (2.5%) carried the CHEK2 1100delC mutation compared to 1% in the control group." (PMID 16539695, 2006). "The rare 1100delC mutation in the CHEK2 gene has been associated with breast tumours of high grade, in addition to steroid receptor-positive breast tumours, but not with overall survival." (PMID 17132159, 2006). "In this model the presence of a germ line CHEK2*1100delC mutation might be regarded as an accelerator of tumorigenesis leading to CNA profiles comparable to that of luminal sporadic breast tumors." (PMID 26553136, 2015). "Further studies are needed to establish whether this loss is indeed associated with CHEK2 breast tumors." (PMID 26553136, 2015). "The breast tumor of the patient harboring the p.P92R missense mutation was positive for ER, which is consistent with previous findings that breast tumors linked with CHEK2 frame shift and missense mutations (c.1100delC, c.IVS2 +1G>A, del5395, p.I157T) are predominantly ER-positive." (PMID 23806170, 2013).
breast tumors (continued). "Also, BRCA1 mutated breast tumors are frequently reported to be of the basal-like intrinsic subtype, opposed to breast tumors from CHEK2 mutation carriers, which are reported to be mostly steroid hormone receptor positive (progesterone receptor/progesterone receptor (ER/PR) positive)." (PMID 26553136, 2015). "The research also mentions that the detection of mutations in CHEK2 can be used as a prognostic factor for patient response to treatment and for targeting molecules involved in the proliferation of breast tumor cells that are downstream of CHEK2." (PMID 35885460, 2022). "In consistent with the fact that circPGR regulates the expression of CDK1, CDK6 and CHEK2, the expression of these genes was significantly higher in ER-positive breast tumor tissues compared to that of adjacent normal tissues." (PMID 33408778, 2021). "In the clinical classification of the relationship of the CHEK2 gene with HBOC, the association is considered “definitive” for breast tumors." (PMID 33134171, 2020). "Our analyses suggest that there are fundamental differences in breast tumors of CHEK2:p.I157T and c.1100delC carriers." (PMID 27716369, 2016). "In total, 126 breast tumor tissue specimens including 32 samples from patients carrying CHEK2 1100delC were studied in array-comparative genomic hybridization (aCGH) and gene-expression (GEX) experiments." (PMID 21542898, 2011). "The existence of neighboring driver genes is one possibility to explain the elevated expression OR genes in CHEK2 1100delC breast tumors." (PMID 21542898, 2011). "We have previously shown that carriers of the truncating CHEK2 c.1100delC mutation often have reduced or absent CHEK2 protein expression in breast tumors." (PMID 25918678, 2015). "Two other studies found markedly reduced expression of CHK2 in breast tumours from CHK2 carriers, although this was not always accompanied by loss of heterozygosity (LOH) at CHEK2." (PMID 15700044, 2005). "In addition, alternative splicing expression profile was also successfully used in several studies aiming to discriminate subtypes of breast tumors, and specific gene expression profiles have also been identified for BRCA1, BRCA2 and CHEK2-associated breast tumors." (PMID 29108258, 2017). "The gene expression investigations revealed the substantial down-regulation of BRCA1 (P = 0.02), CHEK2 (P = < 0.0001), BRIP1 (P = < 0.0001), and RAD51 (P = 0.01) in breast tumors compared with adjacent normal tissues." (PMID 35715772, 2022). "Since our data about miR-182-5p expression indicate its remarkable up expression in breast tumors, especially in TNBC and its potential effects on downregulating CHEK2 and RAD51 in TNBC, we examined the level of cell-free miR-182-5p in the blood plasma samples from the patients." (PMID 35715772, 2022). "Such factors may not be needed for breast tumors with a defect in a non-essential gene such as CHEK2." (PMID 26553136, 2015). "Our observation followed by statistical analysis of methylation status in breast tumors along with transcript expression revealed a negative correlation for TRAIL, DR4, CASP8, ATM, CHEK2, BRCA1 and BRCA2 CpG sites." (PMID 21092294, 2010).